PGR (progesterone receptor)
Diseases named in the same sentence as PGR in open-access papers (continued):
Sharing a sentence is not in itself a finding about the gene and the disease.
leiomyoma (continued). "The leiomyoma, by far the most common of all the neoplasms, is generally hormone sensitive, with rates of growth semi-quantitatively related to estrogen and progesterone receptor levels." (PMID 24238671, 2013). "Progesterone receptor modulators, such as mifepristone are useful and well tolerated in reducing leiomyoma volume although with large individual variation." (PMID 24324590, 2013). "Estrogen receptor and progesterone receptor in case of benign metastasizing leiomyoma usually have high expression, and drugs or ovariectomy can make the lesions regress or remain stabilized." (PMID 23234399, 2012). "Progesterone, through its receptor, PGR also increase leiomyoma growth via inhibiting apoptosis and promoting cell proliferation." (PMID 22570742, 2012). "In addition, although our analysis focused on ER expression in relation to CDK8 activity, the progesterone receptor (PR) also plays a key role in leiomyoma growth." (PMID 41493967, 2026). "Histopathological examination revealed a leiomyoma with prominent angioleiomyomatous features, characterized by spindle cells surrounding thick-walled vascular structures and immunopositivity for desmin, smooth muscle actin, and progesterone receptor." (PMID 40978684, 2025). "Treatments for these masses include selective progesterone receptor modulators and gonadotropin-releasing hormone analogues, hysterectomies for symptomatic uterine fibroids, myomectomies if fertility retention is desired, and uterine artery embolization for more conservative interventions." (PMID 40585699, 2025). "Compared with premenopausal leiomyomas, the expression of progesterone receptor decreased." (PMID 35974345, 2022). "A selective progesterone receptor modulator (SPRM), ulipristal acetate (UPA), was registered as a drug in preoperative management of symptomatic myomas in order to reduce the size of tumors and eliminate abnormal uterine bleeding associated with fibroids." (PMID 33546154, 2021). "However, one of the major roles of estrogens in the multistep fibroid development appears to be the induction of progesterone receptor expression rendering the leiomyoma tissue more responsive to progesterone signals." (PMID 28930160, 2017). "Thus, the use of selective progesterone receptor modulators (SPRMs) for leiomyoma treatment has been explored and previously addressed in fourteen clinical studies, among which only two were placebo controlled." (PMID 24324590, 2013). "Leiomyoma of the nipple has recently been reported to be estrogen and progesterone receptor positive therefore the appearance and progression of the tumor might have a possible relation to the medical history of contraceptive administration to the patient." (PMID 23421917, 2013). "Upregulation of ESR1, PGR and aromatase in leiomyoma tissue were reported." (PMID 22570742, 2012). "It is conceivable that MED12-mutation-positive and -negative leiomyomas may respond differently to hormone-level changes, as well as to treatments, such as selective progesterone receptor modulators." (PMID 28432313, 2017). "For comparison of differential expression of genes in leiomyomas, there was a significant race/ethnicity correlation in expression for TNFRSF19, IRS4, PLEKHG4B, PGR, KRT17, CCDC177, MYO5B, and ZNF703." (PMID 37686244, 2023). "UPA is widely used as a selective progesterone receptor modulator and was approved by the US FDA in 2010 for treating symptomatic leiomyoma in females of childbearing age." (PMID 36313223, 2022). "Amongst those, gonadotropin-releasing hormone agonists (GnRHa) and selective progesterone receptor modulator (SPRM), in particular, have been assessed and approved for treatment of fibroids." (PMID 32012826, 2020).
leiomyoma (continued). "What is the impact of administration of the selective progesterone receptor modulator (SPRM), ulipristal acetate (UPA) on the endometrium of women with fibroids?" (PMID 28130434, 2017). "Both, in culture of isolated human leiomyoma cells, and in culture of whole tissue pieces preserving the characteristic extracellular matrix, ESR1 and PGR mRNA are strongly downregulated within hours." (PMID 26588841, 2015). "The steroid hormone receptors, ESR1 and PGR, and smooth muscle cell markers were expressed at the same level in LMSP, LMMP, and cultured cells from whole leiomyoma tissue." (PMID 22570742, 2012). "The authors further demonstrate that while 17β-estradiol alone does not stimulate proliferation, 17β-estradiol induces PGR expression and supports progesterone action on the leiomyoma xenografts." (PMID 35203298, 2022). "Many patients with malignant change of LPD exhibit no exogenous estrogen stimulation, estrogen and progesterone receptor negativity within the tumor, and no leiomyoma." (PMID 26215629, 2015). "In this vein, asoprisnil, a steroidal 11β-benzaldoxime-substituted selective progesterone receptor modulator (SPRM), targets TGFB3 and TGFBR2 in leiomyoma cells but not normal myometrial cells, providing a potentially effective treatment option for leiomyoma." (PMID 25478164, 2014). "Earlier studies in fibroid research demonstrated that cultured leiomyoma cells responded to 100 ng/mL of UPA (also known as CDB-2914; CDB-2914 (17α-acetoxy-11β-[4-N,N-dimethylaminophenyl]-19-norpregna-4,9-diene-3,20-dione) by regulating progesterone receptor (PR) isoforms." (PMID 34356998, 2021). "The development of a new class of synthetic compounds the ‘selective progesterone receptor modulators’ (SPRMs) exhibiting mixed agonist and antagonist activity appears to offer a new approach to medical management of hormone dependent uterine disorders such as HMB and fibroids." (PMID 28130434, 2017).
ductal carcinoma (32 papers, 2002 to 2025). "Multivariate analysis indicated that YKL-40 intratumoral expression, YKL-40 serum concentrations, invasive lobular and ductal carcinomas, and progesterone receptor expression were associated with shorter disease-free survival." (PMID 23227243, 2012). "IDC: Invasive lobular carcinoma; ILC: Invasive ductal carcinoma; IHC: Immunohistochemistry; ER: Estrogen receptor; PR: Progesterone receptor; HER2: Human epidermal growth factor receptor 2; ECOG: Eastern Cooperative Oncology Group." (PMID 39469406, 2024). "The breast tumour of this patient was ER-positive and progesterone receptor (PR)-positive ductal carcinoma with grade 3." (PMID 38036545, 2023). "Most patients had grade 3 (10/19, 53%) ductal carcinoma (15/19, 79%), estrogen receptor-positive (12/19, 63%), progesterone receptor positive (12/19, 63%), and human epidermal growth factor receptor 2 (HER-2) negative (15/19, 79%)." (PMID 36518323, 2022). "Ductal carcinomas showed low ESR1/PGR and PRLR gene expression as well, even though it has been shown that they have a low tendency to invade lymphatic vessel." (PMID 27649560, 2016). "The majority of the BC patients were at clinical cancer stage T0–T2 (74%) and were predominantly estrogen receptor (ER) positive (66%), progesterone receptor (PR) positive (59%), and ductal carcinoma (94%) with a well differentiated/moderately differentiated (G1/G2) tumor histological grade (68%)." (PMID 36293492, 2022). "Two years previously, the patient had undergone conservative breast surgery for high-grade ductal carcinoma of the right breast [stage I; estrogen receptor (ER)-positive, 90%; progesterone receptor (PgR)-positive; 80%; human epidermal growth factor 2-negative; Ki67 labeling index, 10%]." (PMID 25120706, 2014). "These patients were at least 60 years old when the original study started, had a mix of progesterone receptor presence, were primarily HER2-negative, and consisted mostly of ductal carcinoma." (PMID 39057065, 2024). "Among the histological subtypes the lowest gene expression levels of ESR1, PGR and PRLR were found in solid, anaplastic and ductal carcinomas." (PMID 27649560, 2016). "Most patients were postmenopausal (66.7%), estrogen receptor positive (67.4%), progesterone receptor negative (52.1%), fluorescence in situ hybridization amplified (88.4%), and had ductal carcinoma (87.7%) and Nottingham histological grade ≥2 (85.2%)." (PMID 39263806, 2024). "Following this diagnosis, immunohistochemical studies for hormone receptors showed estrogen receptor 0.97% expression, progesterone receptor 1.68% expression, and HER2 score 3+ by immunohistochemistry (IHC), correlating with the known primary left breast ductal carcinoma." (PMID 39022491, 2024). "Patient A was diagnosed with a 40 mm ductal carcinoma of the right breast, G3 ER, PgR and HER2 negative, 90% Ki67." (PMID 34068368, 2021). "At 38 years she presented a poorly differentiated ductal carcinoma of the right breast, pT1cN1mi(1/3) G3, estrogen receptor (ER) positive 90%, progesterone receptor (PgR) positive 40%, HER2 negative, KI67 40%." (PMID 31673247, 2019). "Furthermore, the gene expression of ESR1, PGR and PRLR were significantly lower in solid, anaplastic and ductal carcinomas compared to the reference tissue." (PMID 27649560, 2016). "PGR expression levels were significantly lower in solid carcinomas (p = 0.042), anaplastic carcinomas (p = 0.011) and ductal carcinomas (p = 0.036) than the non-neoplastic mammary tissue of fresh frozen samples when comparing the histological subtypes." (PMID 27649560, 2016). "Subsequent histopathological examination determined an invasive, grade two, estrogen and progesterone receptor (ER and PR)-positive (score 3+), HER2-negative ductal carcinoma lesion of the breast (diameter, 2.5 cm) and metastasis to one of the axillary lymph nodes." (PMID 25621073, 2015).
ductal carcinoma (continued). "Additionally, similar proportions of patients in each group were estrogen or progesterone receptor positive or negative, had ductal or non-ductal breast carcinoma, and received prior radiotherapy or hormonal therapy." (PMID 27016084, 2016). "ER and PgR analysis may not always be contributory because a large number of high-grade ductal carcinomas are ER/PgR negative." (PMID 20806071, 2010). "When NEBC were compared to ductal carcinomas (n=925), NEBC were more often human epidermal growth factor receptor 2 negative (p=0.039), estrogen receptor positive (p=0.05), progesterone receptor positive (0.03), and the NEBC patients were older (p=0.02)." (PMID 35317367, 2021). "Immunohistochemically, the ductal carcinoma cells were positive for CK AE1/AE3 but not ER, PgR, or HER2." (PMID 20731838, 2010).
invasive lobular carcinoma (32 papers, 2008 to 2025). "The pathologic diagnosis at both the middle and posterior biopsy site was invasive lobular carcinoma, intermediate grade, and estrogen receptor/progesterone receptor (ER/PR) positive." (PMID 39981491, 2025). "In the following case report, we describe the rare presentation of a patient diagnosed by punch biopsy with grade III, estrogen receptor (ER)-/progesterone receptor (PR)-positive invasive lobular carcinoma with intradermal invasion." (PMID 36043018, 2022). "Estrogen receptor positivity (P < 0.001), progesterone receptor positivity (P = 0.010), invasive lobular carcinoma (P = 0.009) and receiving endocrine therapy (P = 0.001) predicted longer TTR." (PMID 35076871, 2022). "Bone marrow biopsy showed metastatic carcinoma positive for estrogen receptor and progesterone receptor, consistent with invasive lobular carcinoma of breast." (PMID 28174654, 2017). "Based on the pathological findings, axillary lymph node metastasis of invasive lobular carcinoma (ER-positive, PgR-positive, and HER2-negative) was diagnosed." (PMID 27350919, 2016). "The right-sided breast mass was biopsied and this confirmed an invasive lobular adenocarcinoma (Grade 2), that was both strongly ER and progesterone receptor (PR) positive, with a H-score of 280 and 220 respectively." (PMID 19046426, 2008). "Patients with AKT pathway mutations were older (p = 0.002) and had a higher rate of invasive lobular carcinoma (ILC) histology (p = 0.001), progesterone receptor (PgR) positivity (p = 0.006), and bone metastases (p = 0.001), and a lower rate of germline BRCA2 (p < 0.001)." (PMID 39466567, 2025). "Invasive lobular breast carcinomas (ILBCs) represent 10–15% of all invasive breast tumors and, in the majority of cases, express hormone receptors [estrogen receptor (ER) and progesterone receptor (PR)] and lack HER2 protein expression and/or gene amplification." (PMID 38335502, 2024). "An immunohistochemical panel consisting of estrogen receptor (ER), progesterone receptor (PR), gross cystic disease fluid protein (GCDFP-15), mammoglobin, and GATA3 can be useful in differentiating invasive lobular breast carcinoma." (PMID 34514560, 2021). "It was an invasive lobular carcinoma with a grade II of the Scarff–Bloom–Richardson (SBR) classification and positive hormonal receptors [estrogen receptor (ER), progesterone receptor (PR)]." (PMID 34330331, 2021). "We applied the factor analysis pipeline to a human invasive lobular carcinoma breast tissue (estrogen receptor positive, progesterone receptor positive, and HER2 negative) dataset that contains transcriptomics measurements profiled across 4325 spots." (PMID 38331751, 2024). "Final pathology revealed 5.5 cm tumor containing grade 2 invasive lobular carcinoma that was estrogen receptor (ER) and progesterone receptor (PR) positive, and Her2/neu negative." (PMID 31818306, 2019). "A core needle biopsy of the breast mass showed low-grade, estrogen receptor/ progesterone receptor (ER/PR)-positive, human epidermal growth factor receptor 2 (HER2)-negative invasive lobular carcinoma." (PMID 39723327, 2024). "Our patient’s pathological examination revealed characteristics of an invasive lobular carcinoma, including a row of small cells (Indian file), negative staining for E-cadherin and HER2, and positive staining for both ER and PgR." (PMID 25902937, 2015).
uterine fibroids (32 papers, 2012 to 2025). "Given the prevalence, and morbidity, associated with uterine leiomyoma the promise of a long-term medical solution is encouraging with the advent of selective progesterone receptor modulators, most notably ulipristal acetate." (PMID 29780819, 2018). "Selective progesterone receptor modulators (SPRMs) play an important role in the medical treatment of uterine fibroids by targeting progesterone-driven pathways that promote fibroid growth." (PMID 41010699, 2025). "Both LGESS and uterine leiomyomas can manifest during the premenopausal and perimenopausal periods, frequently exhibit similar clinical progressions, and express ER and PgR." (PMID 40225539, 2025). "Here, we reported that estrogen receptor alpha and progesterone receptor mediated the occurrence and development of uterine leiomyoma and that estrogen receptor beta involved in the angiogenesis, which explained the effectiveness of hormonotherapy." (PMID 37215998, 2023). "ERα and PGR mediated the occurrence and development of uterine leiomyoma and ERβ involved in the angiogenesis, which explained the effectiveness of hormonotherapy." (PMID 37215998, 2023). "Especially, the newest medical treatment options, such like gonadotropin-releasing hormone (GnRH) analogs, GnRH antagonists and selective progesterone receptor modulators, for symptomatic Uterine fibroids are now developed for women with uterine fibroids." (PMID 36138425, 2022). "UPA is a selective progesterone receptor modulator (SPRM) which is proposed for the treatment of several gynecological conditions including uterine fibroids and endometriosis." (PMID 33893356, 2021). "Only PgR expression was higher in women with a burdened history of uterine fibroids (p = 0.008), especially in sisters (p = 0.015)." (PMID 34449552, 2021). "PgR expression was stronger in women with a history of uterine fibroids, especially in relation to sisters (p = 0.015)." (PMID 34449552, 2021). "To date, this is the longest reported experience using a selective progesterone receptor modulator (SPRM) in the medical management of uterine fibroids." (PMID 28267814, 2017). "Ulipristal acetate is a selective progesterone receptor modulator (SPRM) already approved for the treatment of uterine fibroids in Europe." (PMID 25143845, 2014). "Background/Objectives: Ulipristal acetate (UPA) is a selective progesterone receptor modulator approved for the treatment of uterine fibroids, but concerns have arisen regarding its potential for severe hepatotoxicity, particularly following regulatory warnings in Europe and Korea." (PMID 41010699, 2025). "Estrogen receptor- and progesterone receptor-positivity are specific for uterine leiomyomas and may be helpful in diagnosing parasitic leiomyoma." (PMID 39221350, 2024). "On primary cultures of human uterine leiomyoma cells, it was shown that adrenergic receptor agonists modulate estrogen receptor (ER), progesterone receptor (PR), vascular endothelial growth factor (VEGF), and fibroblast growth factors (FGF), influencing cell proliferation." (PMID 36471219, 2023). "Additionally, statistically more frequent PgR expression was found in cases of familial uterine fibroids (p = 0.008)." (PMID 34449552, 2021). "Thus, the spontaneous pregnancy after UA to reduce fibroid size may support the potential clinical utility of this selective progesterone receptor modulator in the management of women with pregnancy desire and uterine fibroids after a prior myomectomy." (PMID 25143845, 2014). "Ulipristal acetate (UPA), a selective progesterone receptor modulator (SPRM), was introduced as a novel medical therapy for uterine fibroids, offering sustained fibroid shrinkage, symptom relief, and better tolerability compared to traditional agents." (PMID 41010699, 2025).
uterine fibroids (continued). "Ulipristal acetate (UPA), a selective progesterone receptor modulator (SPRM), has been gaining attention for the treatment of uterine fibroids in recent years." (PMID 35036597, 2022). "Ulipristal acetate (UPA) is a selective progesterone receptor modulator (SPRM) used for emergency contraception and for the medical management of symptomatic uterine fibroids (UF)." (PMID 30013514, 2018). "Selective progesterone receptor modulators (SPRMs) offer novel and unique medical treatment options in gynecology and the potential of SPRM for the treatment of uterine fibroids has been well established." (PMID 28267814, 2017). "However, DPL with uterine leiomyomas has a low risk potential for malignant transformation, whereas DPL without exposure to estrogen, without uterine leiomyomas, and without ER and PgR expression may have a high malignant potential." (PMID 31410732, 2019). "The progesterone receptor modulator CDB-2914, induces MMP expression, including MMP8, in uterine leiomyoma cells, but MMP8 is not activated by this treatment and its role remains unclear." (PMID 31514474, 2019).